PTGIS (prostaglandin I2 synthase)
Diseases named in the same sentence as PTGIS in open-access papers (continued):
Sharing a sentence is not in itself a finding about the gene and the disease.
gastric cancer (6 papers, 2020 to 2024). A primary or metastatic malignant neoplasm involving the stomach. "Kaplan-Meier plotter showed that high PTGIS was associated with poor overall survival and progression-free survival in lung, ovarian, and gastric cancers." (PMID 32463792, 2020). "To explore the potential mechanism by which PTGIS expression affects prognosis, we studied the association between expression levels of PTGIS and clinical variables in ovarian and gastric cancer patients." (PMID 32463792, 2020). "We found that PTGIS expression was associated with tumor immune cell infiltration in lung, ovarian, and gastric cancers." (PMID 32463792, 2020). "High PTGIS expression can promote infiltration of immune cells, such as tumor-associated macrophages and regulatory T cells, into the tumor microenvironment, which impairs the prognosis of patients with lung, ovarian, and gastric cancer." (PMID 37628631, 2023). "High expression of PTGIS could promote the infiltration of tumor-associated macrophages and Tregs in the tumor microenvironment and deteriorate outcomes of patients with lung, ovarian, and gastric cancers." (PMID 36785673, 2023). "In summary, these results powerfully demonstrate that PTGIS is a prognostic marker for lung, ovarian, and gastric cancers." (PMID 32463792, 2020). "For gastric cancer patients, compared with lower levels of PTGIS, elevated PTGIS was correlated with worse OS and PFS after stratification by HER2 status, Lauren classification, or differentiation (P < 0.05)." (PMID 32463792, 2020). "Based on this large-sample validation analysis, these results suggest that high PTGIS expression implies reduced survival in ovarian, lung and gastric cancer." (PMID 32463792, 2020). "In addition, in lung, ovarian, and gastric cancers, the PTGIS expression level was closely related to the activation of immune cells, especially TAMs and Tregs, as well as T cell exhaustion." (PMID 32463792, 2020). "Notably, high expression of PTGIS could significantly impair the prognosis of patients with lymph node metastasis in ovarian or gastric cancer." (PMID 32463792, 2020). "Thus, PTGIS may play a role of immune suppression by affecting tumor-infiltrating immune cells and be used as a prognostic marker for lung, ovarian and gastric cancer patients." (PMID 32463792, 2020).
ovarian carcinoma (6 papers, 2020 to 2024). A malignant neoplasm originating from the surface ovarian epithelium. "In view of the association of PTGIS with a poor clinical outcome of ovarian cancer, targeting PGI2 synthesis either directly, or indirectly via COX inhibition, may be a promising option to improve the treatment of HGSC patients." (PMID 36551640, 2022). "PGI2 has been described to act as an anti-metastatic mediator in lung cancer mouse models and to suppress ovarian cancer cell invasion by MMP2/MMP9 downregulation in vitro, whereas other studies reported an association of PTGIS expression with reduced survival of breast and ovarian cancer patients." (PMID 36551640, 2022). "Little research has investigated the possible involvement of PTGIS in ovarian cancer, which is one of the study's strengths." (PMID 36785673, 2023). "The PGRMC1 (Membrane-associated progesterone receptor component 1) is known to be involved in ovarian cancer as well as PTGIS (Prostacyclin synthase) and the Protein NDRG1 known to modulate genes involved in ovarian cancer metastasis." (PMID 37775701, 2023). "PTGIS may be an indicator of prognosis and a possible therapeutic target for the therapy of ovarian cancer patients." (PMID 36785673, 2023). "However, the role and mechanism of PTGIS in ovarian cancer are still unclear, and few studies have been conducted." (PMID 36785673, 2023). "Finally, PTGIS may serve as a prognostic indicator and therapeutic target for patients with ovarian cancer." (PMID 36785673, 2023). "Mutations in PKCθ have been detected in lymphomas and leukemias, including 2 fusion proteins (FAM107B-PRKCQ and PTGIS-PRKCQ, respectively), with two additional fusion proteins being detected in breast and ovarian cancers." (PMID 38752473, 2024).
atherosclerosis (5 papers, 2020 to 2024). A disease characterized by the build-up of fatty material and calcium deposition in the arterial wall resulting in partial or complete occlusion of the arterial lumen. "STAT1 has been identified as a possible therapeutic target for atherosclerosis, and PKM and PTGIS have been identified as risk markers of atherosclerosis." (PMID 39796045, 2024). "The expression levels of hs-CRP, TNF-α, NO and EDN1, PTGIS, and AGT genes at risk of atherosclerosis were significantly decreased." (PMID 36180828, 2022). "It is known that PTGIS expression and PGI2 production are associated with shear stress and that PGI2 deficiency may contribute to the development of atherosclerosis." (PMID 37189834, 2023). "The role of PTGIS in inflammatory diseases is controversial, as it promotes progression of rheumatoid arthritis yet suppresses progression of pulmonary vascular disease and atherosclerosis." (PMID 36339397, 2022). "Subsequently, genes related to the atherosclerosis indicators EDN1, PTGIS, AGT, NOS3, ICAM1, and VCAM1 were detected by qPCR." (PMID 36180828, 2022).
bladder cancer (5 papers, 2018 to 2023). "In another study, the PTGIS gene is related to bladder cancer’s ability to proliferate, migrate and undergo epithelial-mesenchymal transition." (PMID 37256175, 2023). "Combined with TCGA, we also found out that the PTGIS could predict the prognosis of bladder cancer which further illustrated that the reduction of PGI2 might be one of the results in the UC’s occurrence and development." (PMID 37256175, 2023). "Furthermore, PTGIS is involved in regulating the malignant behavior of bladder cancer under hypoxic conditions." (PMID 37796199, 2023). "Taken together, our study indicated that CIRBP could be a novel oncogene in human bladder cancer inducing transcription of HIF-1α, which could inhibit expression of methylated PTGIS." (PMID 30315244, 2018).
endometriosis (5 papers, 2020 to 2024). The growth of functional endometrial tissue in anatomic sites outside the uterine body. "According to western blot analysis, the protein levels of LY96, PDLIM3, and PTGIS were higher in the tissues of endometriosis patients." (PMID 36339397, 2022). "Considering the pivotal role of M2 in endometriosis, we speculated that elevated PTGIS may also exert its function by influencing macrophage polarization." (PMID 38549776, 2024). "Quantitative assessments of histological images clearly demonstrated higher expression levels of LY96, PDLIM3, PTGIS, and WISP2, proteins in tissues from patients with endometriosis, in line with integrative analysis results." (PMID 36339397, 2022). "Zhao Dong at Tongji University in Shanghai, China, and co-workers used human tissue samples and mouse models to determine the roles of a metabolite called prostacyclin (PGI2) and its catalytic enzyme (prostacyclin synthase, PTGIS) in endometriosis." (PMID 35781537, 2022). "The overexpression of PTGIS, functioning to convert prostaglandin H2 (PGH2) to prostaglandin I2 (PGI2), whose higher expression in the peritoneal fluid was observed in patients with endometriosis, had also been found a previous study." (PMID 32185115, 2020). "In the context of endometriosis, PTGIS has been shown to regulate disease progression through its influence on CD16-NK cells, although no studies have been reported on PTGIS in the context of EC." (PMID 37796199, 2023).
Hypertension (5 papers, 2010 to 2024). The presence of chronic increased pressure in the systemic arterial system. "Experimental studies confirmed that PTGIS is associated with essential hypertension in humans and that transgenic rats highly expressing human PTGIS exhibited decreased mean pulmonary arterial pressure despite treatment with monocrotaline to induce hypertension." (PMID 20957118, 2010). "PTGIS is a well-known marker gene for cardiovascular diseases and hypertension." (PMID 35627272, 2022). "The evidence resulting from this study suggests that PTGIS and ACOX1 are both potential causal torcetrapib off-targets, the inhibition of which may explain the side effect of hypertension." (PMID 20957118, 2010). "The data indicated that several DEGs, including prostaglandin I2 (prostacyclin) synthase (PTGIS), RGS5, selectin E (SELE), endothelin converting enzyme (ECE), and ATPase, Na+/K+ transporting, and beta 1 polypeptide (ATP1B1), were highly associated with hypertensive disease." (PMID 32041970, 2020). "The heart proteins ADD3, PTGIS, and COL1A2 are candidates for hypertension and myocardial infarction." (PMID 35259090, 2022).
prostate carcinoma (4 papers, 2015 to 2024). A carcinoma that arises from epithelial cells of the prostate gland. "A recent study found that rsRNA‐28S could directly target the 3′ untranslated region of the prostaglandin I2 synthase gene to downregulate its expression and attenuate the chemoresistance of prostate cancer cells." (PMID 39051629, 2024).
head and neck cancer (3 papers, 2020 to 2023). A primary or metastatic malignant neoplasm affecting the head and neck. "Additionally, PTGIS mRNA and protein expression level was found to be lower in head and neck carcinoma tissues, and low PTGIS mRNA expression was correlated with poor survival of head and neck carcinoma patients." (PMID 35513851, 2022).
colon adenocarcinoma (2 papers, 2020 to 2023). "In the UALCAN database, PTGIS gene expression was lower in colon adenocarcinoma tissues (N = 286) compared with normal colorectal tissues (N = 41), and the difference was statistically significant (p = 1.900700e−03)." (PMID 37779109, 2023). "Obviously, compared with normal tissues, the PTGIS gene showed low expression in colon adenocarcinoma and rectal adenocarcinoma, and the difference was statistically significant (P < 0.05)." (PMID 37779109, 2023).
idiopathic pulmonary arterial hypertension (2 papers, 2015 to 2020). A sporadic form of pulmonary arterial hypertension (PAH) characterized by elevated pulmonary arterial resistance leading to right heart failure. "The rare variants of the PTGIS gene appear to contribute higher susceptibility to idiopathic pulmonary arterial hypertension, and screening of PTGIS variants may help improve personalized treatment of these patients." (PMID 32236489, 2020).
ischemic stroke (2 papers, 2017 to 2019). A stroke disorder caused by obstruction of blood flow to the brain, due to thrombotic (local blood clot formation) or embolic (due to a blood clot or other material traveling from another site) event. "The frequencies of PTGIS (rs5602CC) and PTGS2 (rs20417CC) variants were significantly higher in patients with carotid plaque compared with patients without plaque, and are associated with carotid plaque vulnerability, platelet activation and TXA2 levels in ischemic stroke patients." (PMID 31539405, 2019).
Myocardial fibrosis (2 papers, 2022 to 2024). "The expression of PTGIS was lower in the PAF group compared with those in SR controls at both mRNA level and protein level, accompanied by elevated alpha-smooth muscle actin (α-SMA) levels, and subepicardial and myocardial fibrosis." (PMID 38878214, 2024).
non-small cell lung carcinoma (2 papers, 2015 to 2022). A group of at least three distinct histological types of lung cancer, including non-small cell squamous cell carcinoma, adenocarcinoma, and large cell carcinoma. "In one study, reduced PTGIS expression was observed in human non-small cell lung cancer compared with that in controls." (PMID 35513851, 2022).
oral cancer (2 papers, 2016 to 2020). "Somatic mutations in arachidonic acid metabolism pathway genes, such as PLA2G3, PTGIS and GGT7, prolong post-treatment disease-free survival of patients with oral cancer." (PMID 27888627, 2016).
ovarian tumors (2 papers, 2022 to 2023). "The future study will examine the relationship between PTGIS and lipid metabolism molecules such as PPAR, FABP4, FASN, and CD36, as well as the effect of fatty acid metabolism on the growth and invasion of ovarian tumorous cells." (PMID 36785673, 2023).
steatosis (2 papers, 2018 to 2021). Increased lipid within the cytoplasm of cells. "Histologically, H&E staining and Masson trichrome staining showed that forced expression of PTGIS could alleviate steatosis, necrosis and collagen deposition." (PMID 29892223, 2018).
abdominal aortic aneurysm (1 paper, 2022). Enlargement and ballooning of the vessel that supplies arterial blood to the abdomen, pelvis and legs. "Additionally, miR-150-5p is referred to in the literature as being involved in the regulation of genes with a role in eicosanoid synthesis, such as PTGIS and the MMP/TIMP pathway, which are implicated in the pathogenesis of abdominal aortic aneurysm (AAA)." (PMID 36496981, 2022).
asthma (1 paper, 2017). "However, PTGIS is the only one of these mRNA targets to have been associated with ASM and can induce both bronchodilation and reverse ASMC remodeling in a mouse model of asthma." (PMID 27484035, 2017).
COVID-19 (1 paper, 2021). A disease caused by infection with severe acute respiratory syndrome coronavirus 2. "In addition, PTGIS possesses anti-inflammatory properties by modulating the expression of interleukin-1 (IL-1), IL-6, and IL-10, which may be associated with COVID-19 severity." (PMID 34315889, 2021).
embryonic carcinoma (1 paper, 2017). "The SNV is in the first intron of PTGIS, overlapping DNase I hypersensitivity regions, potential ZNF217 transcription factor binding sites and H3K36me3 histone mark signatures in the NT2-D1 (pluripotent embryonic carcinoma) cell line." (PMID 28448578, 2017).
melanoma (1 paper, 2022). A malignant, usually aggressive tumor composed of atypical, neoplastic melanocytes. "muTARGET web-based tool allowed us to predict genes, which expression patterns can be associated with genetic polymorphism in group #1 (TBXAS1, PTGIS, and AKR1C3) or group #2 (PTGDR, PTGFR, and PTGER3) in melanoma." (PMID 35453789, 2022). "Mutation frequency of TBXAS1, PTGIS, AKR1C3, PTGDR, PTGFR and PTGER3 genes in melanoma were 5–6%, 5–7%, 2.8–5%, 3–4%, 7–9%, 2.1–5%, respectively." (PMID 35453789, 2022).
Obesity (1 paper, 2022). Accumulation of substantial excess body fat. "Among them, the upregulated gene BCL2A1 is common in CVD, HTN, obesity, and aging; RNF144B and PTGIS are common in HCL, obesity, aging, and CVD; G0S2, CXCL1, ACKR3, and PTPRD are found in HTN, aging, and CVD; TGFB2, CA12, and MSR1 are familiar in obesity, aging, and CVD." (PMID 36035865, 2022).
pancreatic adenocarcinoma (1 paper, 2023). "Another example is the expression of PGIS/PTGIS, decreased in 17 types of cancer but elevated only in pancreatic adenocarcinoma." (PMID 36765904, 2023).
pancreatic ductal adenocarcinoma (1 paper, 2022). An infiltrating adenocarcinoma that arises from the epithelial cells of the pancreas. "In patient samples, we identified a transition from PGD2- to PGE2-producing enzymes in the epithelium during the transition to pancreatic ductal adenocarcinoma, fibroblast/tumor expression of PTGIS, and myeloid/tumor cell expression of TBXAS1." (PMID 36277993, 2022).
Patent ductus arteriosus (1 paper, 2022). In utero, the ductus arteriosus (DA) serves to divert ventricular output away from the lungs and toward the placenta by connecting the main pulmonary artery to the descending aorta. "DNA polymorphisms in PTGIS and TFAP2B have been identified as risk factors for patent ductus arteriosus (PDA) in a population composed of preterm infants with European genetic ancestry but not in more genetically diverse populations." (PMID 33837257, 2022).
rectal adenocarcinoma (1 paper, 2023). "Comparing normal rectal tissues (n = 10) and rectal adenocarcinoma tissues (N = 166), PTGIS gene was found to be significantly lower in rectal adenocarcinoma (p = 3.8442999999991e−06)." (PMID 37779109, 2023).
sarcoma (1 paper, 2020). A usually aggressive malignant neoplasm of the soft tissue or bone. "In addition, elevated PTGIS expression was associated with improved DFS for only SARC (sarcoma)." (PMID 32463792, 2020).
serous ovarian cancer (1 paper, 2020). "For serous ovarian cancer, high expression of PTGIS was related to reduced OS and PFS." (PMID 32463792, 2020).
Stroke (1 paper, 2020). Sudden impairment of blood flow to a part of the brain due to occlusion or rupture of an artery to the brain. "Notably, PTGIS was previously reported to be in the vicinity of a lncRNA that was negatively correlated with time after stroke in male stroke patients, suggesting a role for non-coding RNA in differential gene expression." (PMID 33193047, 2020).
tendon disease (1 paper, 2019). "Biopsies from resolved (pain-free) patients showed increased PTGIS mRNA expression compared to patients with persistent tendon disease (p = 0.03)." (PMID 30867043, 2019).
uterine cancer (1 paper, 2022). Primary or metastatic malignant neoplasm involving the uterine corpus and/or the cervix. "Models of regulation of PTGIS and PTGIR gene expression in lung and uterine cancers were suggested." (PMID 35453789, 2022).
uterine carcinosarcoma (1 paper, 2022). A usually aggressive malignant neoplasm arising from the uterine corpus and less often the cervix. "Regarding the mutational profile, PTGIS exhibited the most mutation frequencies in uterine carcinosarcoma." (PMID 35513851, 2022).